EBF1 (EBF transcription factor 1)
Diseases named in the same sentence as EBF1 in open-access papers (continued):
Sharing a sentence is not in itself a finding about the gene and the disease.
tumor (39 papers, 2004 to 2025). "Epigenetic modification is a key mechanism underlying tumor phenotype development, and growing evidence suggests that EBF1 plays a significant role in the dynamic regulation of DNA methylation in BC." (PMID 40508012, 2025). "This regulatory axis diminishes the tumor-suppressive activity of EBF1 and facilitates cancer progression, highlighting the complexity of upstream modulation within the EBF1-associated anti-tumor network." (PMID 40508012, 2025). "By sequencing the integrations of B ALL samples, recurrent truncating mutations were observed in Ebf1, a tumor suppressor of B ALL which encodes a transcriptional activator of another B cell ALL tumor suppressor Pax5." (PMID 34484175, 2021). "Ebf1 copy number loss occurred in introns 7, 8 and 10 in a single primary tumor, which was verified by qPCR analysis of these regions (data not shown)." (PMID 28692033, 2017). "Strikingly, significant reductions in Ebf1, Tcf3 (encoding E2A), and Runx1 transcripts were observed in tumor compared to unaffected EB cells." (PMID 28692033, 2017). "Additionally, EBF1 has been implicated in maintaining protein homeostasis in tumor cells, further supporting its potential role in promoting CRC progression." (PMID 40508012, 2025). "In addition, we found tumor cell-specific loss of several transcription factors critical for maintaining differentiation: EBF1, TCF3 and RUNX1." (PMID 28692033, 2017). "PHKA2 was identified as an oncogenic factor, whereas SNORD113-3, ADAR2, and EBF1 acted as tumor suppressors." (PMID 39794701, 2025). "At the transcriptional level, various transcription factors exert either activating or repressive effects on EBF1 expression across different tumor types." (PMID 40508012, 2025). "A possible tumor-suppressive role for EBF1 has also been suggested in lung squamous cell carcinoma (LUSC)." (PMID 40508012, 2025). "The functional inactivation of EBF1 can result in losing control of these developmental pathways, leading to tumor phenotypes." (PMID 40508012, 2025). "Beyond its role in shaping the TME, EBF1 also contributes directly to tumor progression within CRC cells." (PMID 40508012, 2025). "Further research has revealed a complex regulatory interplay between EBF1 and long non-coding RNAs (lncRNAs) in bladder cancer (BCa), highlighting their joint involvement in tumor pathophysiology." (PMID 40508012, 2025). "In contrast to its pro-oncogenic roles in certain malignancies, existing studies suggest that EBF1 functions predominantly as a tumor suppressor in prostate cancer (PCa)." (PMID 40508012, 2025). "In contrast to its pro-oncogenic roles in several cancers, EBF1 exhibits clear tumor-suppressive functions in various other solid tumors." (PMID 40508012, 2025). "Early studies generally suggested that EBF1 functions as a tumor suppressor in hematological malignancies." (PMID 40508012, 2025). "Beyond its role in promoting tumor cell aggressiveness, EBF1 has also garnered attention for its involvement in modulating the tumor immune microenvironment (TIME) in BCa." (PMID 40508012, 2025). "EBF1 demonstrates highly context-dependent functions across different solid tumors, acting either as a tumor promoter or suppressor depending on the cellular context, genetic background, and tumor microenvironment." (PMID 40508012, 2025). "Contrary to its pro-tumorigenic roles, EBF1 has also been identified as a potential tumor suppressor in CRC." (PMID 40508012, 2025). "For instance, in CRC, EBF1 can exhibit oncogenic and tumor-suppressive effects, a duality likely driven by tumor heterogeneity." (PMID 40508012, 2025). "Evidence has shown that EBF1 can exert either tumor-suppressive or oncogenic effects across different solid tumors through various signaling pathways, with its molecular mechanisms displaying notable tissue specificity and contextual dependency." (PMID 40508012, 2025).
tumor (continued). "Clustering analysis of tumor cells revealed six subclusters exhibiting transcriptional heterogeneity, including Cp+, Cldn5+, Crabp1+, Ebf1+, Ptprc+, and Srgn+ tumor cells." (PMID 39979981, 2025). "Mechanistically, EBF1 modulates tumor metabolic reprogramming, remodeling of the TME, and maintenance of protein homeostasis by regulating multiple signaling pathways." (PMID 40508012, 2025). "Evidence suggests that EBF1 can act as a tumor suppressor and a promoter of tumor progression, depending on the cellular environment and underlying molecular networks." (PMID 40508012, 2025). "The tumor-suppressive function of EBF1 is primarily attributed to its negative regulation of partner of NOB1 (PNO1), an oncogene involved in ribosome biogenesis." (PMID 40508012, 2025). "Further elucidation of these processes will aid in assessing EBF1’s potential as a therapeutic target and provide a theoretical basis for tumor-type-specific interventions." (PMID 40508012, 2025). "Loss of AKR1B1 attenuated the progression of GC, which is similarly achieved by overexpression of EBF1, while overexpression of AKR1B1 weakened the tumor suppressor activity of EBF1." (PMID 36397644, 2023). "CCA patients with high methylation rates of EBF1 promoter region in the tumor tissues (54/72) had a poor prognosis." (PMID 33854627, 2021). "We observed the increasing tendency of EBFs in the advanced tumor stage for four EBFs, but only EBF1 showed the statistic difference (P<0.05)." (PMID 34100918, 2021). "Our data indicate that EBF1 is highly expressed in peri-endothelial cells in both tumor vessels and in physiological conditions." (PMID 34272603, 2021). "As for tumor grade, we combined Grades 1 and 2 and observed that the expression of EBF1, EBF2, and EBF4 increased in Grade 3 tumors, in comparison with Grades 1 and 2 (all P<0.001)." (PMID 34100918, 2021). "In both cell lines, tumor growth was attenuated in the mice implanted with the EBF1 over-expressing cells These studies indicate that EBF1 over-expression significantly suppresses tumor growth in vitro and in vivo." (PMID 32676457, 2020). "We performed high-throughput sequencing of Ebf1 genes in paired DNA samples comprising EB primary tumor and tail tissue from each host." (PMID 28692033, 2017). "The substantial increase in tumor incidence in CaStat5 mice as a result of Ebf1- or Pax5-haploinsufficiency underscores the importance of these transcription factors in maintaining cellular differentiation despite strong oncogenic signaling." (PMID 28692033, 2017). "ChIP-seq data from ENCODE/PSU shows that areas of Ebf1 genes are enriched with monomethylated histone H3 lysine 4 in a murine B lymphoma cell line, with the regions of copy number loss in the EB54 tumor indicated." (PMID 28692033, 2017). "Tumor development in EB mice likely begins with an accumulation of DNA damage due to reduced Ebf1 dosage, combined with increased cell survival due to high levels of the antiapoptotic BCL-2 family member BCL-XL." (PMID 28692033, 2017). "EBF1 significantly suppressed the proliferation of these cells, in agreement with the previously suggested concept that EBF1 is a tumor suppressor." (PMID 23951143, 2013). "Notably, the anti-cancer effect of LINC00844 was abolished upon EBF1 silencing, confirming that its tumor-suppressive function is strictly EBF1-dependent." (PMID 40508012, 2025). "Beyond its role in tumor cell metabolism, EBF1 also contributes to remodeling the tumor microenvironment (TME), particularly through the activation of cancer-associated fibroblasts (CAFs)—key stromal components whose increased presence is closely linked to BC progression, invasion, and metastasis." (PMID 40508012, 2025). "In addition to targeting AKR1B1, EBF1 also influences tumor progression by interfering with telomerase activity." (PMID 40508012, 2025).
tumor (continued). "In total, recurrent (>3) MEI were observed in 329 protein-coding genes of which 28 genes are annotated in the Cancer Gene Consensus with either oncogenic (ALK1, ERBB4, TSHR, PREX2, CTNNA2, CTNND2) or tumour suppression roles (EBF1, LRP1B, PTPRD, GPC5, ROBO2, PTPRT)." (PMID 35301290, 2022). "Interestingly, we observed selective EBF1 expression within tumor vessels of all the samples analyzed, independently of their histotype." (PMID 34272603, 2021). "To test this hypothesis we searched for EBF1 expression using tissue microarrays and representative sections of tumor samples of different histotypes." (PMID 34272603, 2021). "In addition, EBF1 exhibits tumor suppressive properties in CCA cells through decrease of stemness and oxidative stress-resistant properties via suppressions of Wnt signaling pathway and antioxidants via inhibition of Oct3/4, SOD2 and CAT expression." (PMID 33854627, 2021). "We therefore conclude that the epigenetic therapy could increase EBF1 expression, which contribute to reduce the tumor progression of the cancer cells." (PMID 33854627, 2021). "Furthermore, inducible EBF1 overexpression techniques can be used to confirm an expression-dependent tumor suppressor role for EBF1 in CRC." (PMID 32676457, 2020). "Reductions of Ebf1, Tcf3 and Runx1 transcripts were also detected in EB tumor cells relative to lymph node cells from Bcl-xLTg control mice, confirming that levels of these transcripts are reduced even if the tumor cells are peripheral in origin." (PMID 28692033, 2017). "Therefore, for EBF1 to be considered a viable therapeutic target, it is crucial to clarify its specific roles and elucidate its upstream and downstream regulatory mechanisms in a tumor-type-specific context." (PMID 40508012, 2025). "Furthermore, preliminary findings suggest that EBF1 may regulate interleukin-6 (IL-6) expression, thereby modulating multiple IL-6-related downstream pathways involved in tumor progression." (PMID 40508012, 2025). "Therefore, therapeutic strategies to restore EBF1 expression or activity in specific tumor contexts may have clinical value." (PMID 40508012, 2025). "However, recent literature indicates that its role is context-dependent, and in certain specific types of hematologic cancers, EBF1 may also promote tumor progression." (PMID 40508012, 2025). "However, the study also revealed that elevated levels of another transcription factor, zinc finger protein 521 (ZNF521), in tumor tissues could indirectly promote AKR1B1 expression by suppressing EBF1." (PMID 40508012, 2025). "Treatment of PCa cells with dihydroartemisinin (DHA), an anti-tumor compound, significantly increased the expression of NR2F2, a transcription factor that directly binds to the EBF1 promoter and activates its transcription." (PMID 40508012, 2025). "SNHG14 and LINC00663 interact with EBF1 to enhance its protein stability and functional activity, whereas LINC00844 recruits EBF1 to the GSTP1 promoter to promote its transcription and exert anti-tumor effects." (PMID 40508012, 2025). "Knockdown of the tumor-suppressive lncRNA LINC00261 promotes TC cell proliferation and migration; however, this effect is reversed when EBF1 is concurrently silenced, indicating that EBF1 is a key mediator of the oncogenic pathway downstream of LINC00261." (PMID 40508012, 2025). "In this context, EBF1 was shown to bind to the promoter of COX4I2 directly, enhancing its transcription and contributing to tumor-supportive CAF activation." (PMID 40508012, 2025). "In summary, EBF1 exerts potent tumor-suppressive effects in GC by targeting both AKR1B1 and TERT, and restoring EBF1 expression represents a promising strategy for targeted therapy." (PMID 40508012, 2025).
tumor (continued). "Elevated EBF1 expression subsequently promotes OSCC cell proliferation, migration, and in vivo tumor growth." (PMID 40508012, 2025). "Usually, when analyzing the tumor genome by CMA, aberrations larger than 5 MB and additional microdeletions involving the CDKN2A/B, BTG1, EBF1, ETV6, ERG, IKZF1, PAX5, and RB1 genes are taken into account." (PMID 39408811, 2024). "Compared with the proportion of TF families in the array, we found an over-representation of interactions involving the EBF1, grainyhead, NHR, and AP-2 families, which are known to play important roles in tumor growth and progression via diverse mechanisms." (PMID 39013578, 2024). "An inverse relationship between EBF1 expression and ZNF423 (Zinc Finger Protein 423) levels in tumor tissues leads to unfavourable prognostic outcomes." (PMID 39236081, 2024). "By binding with EBF1, ZNF521 antagonized its transcription repressor function on the expression of AKR1B1, liberating the tumor‐promoting activity of AKR1B1." (PMID 36397644, 2023). "In summary, we report that low EBF1 expression levels in CRC correlates with shorter survival of patients and that EBF1 over-expression suppresses tumor growth by inhibiting cell proliferation and inducing cell apoptosis in CRC cells." (PMID 32676457, 2020). "In this study we report that the transcription factor EBF1 is down-regulated in CRC tissues of patients with poorer outcomes and that EBF1 over-expression suppresses tumor growth in vivo and in vitro by inhibiting proliferation and inducing apoptosis." (PMID 32676457, 2020). "For instance, EBF1 promotes tumor progression in osteosarcoma by regulating non-coding RNA networks." (PMID 40508012, 2025). "This SNHG14/EBF1/FAM171A1 signaling axis has been shown to transform normal fibroblasts (NFs) into pro-tumorigenic CAFs, thereby fostering a microenvironment that supports tumor growth and metastasis." (PMID 40508012, 2025). "In line with the signature prognostic value, from the STRING network analysis emerged an implication of EBF1, MYO6, and CALR in the regulation of tumor progression together with the control of B lymphocyte gene transcription, intracellular vesicle transport and protein folding." (PMID 38035116, 2023). "Recent studies in BC, PDAC, and CCA demonstrate lower EBF1 expression in tumor tissues compared to related non-cancerous tissues." (PMID 32676457, 2020). "Analysis of EBF1 mRNA expression in CRC tumor samples from several public databases and directly from banked tissues revealed that EBF1 mRNA expression is lower in CRC tissue compared to non-cancerous colorectal tissue." (PMID 32676457, 2020). "In addition, EBF1-expressing cells did not express monocyte/macrophage markers CD68, CD163 or Tie-2, recognized markers of tumor-associated macrophages with pro-angiogenic properties." (PMID 34272603, 2021). "However, these particular CpGs were largely demethylated in control non-lymphatic tissue (tail and ear clips) from EB mice, and methylation levels were significantly decreased in lymph node samples from all mice, both EB tumor and Ebf1+/–or Bcl-xLTg controls (data not shown)." (PMID 28692033, 2017). "Although the independent anti-cancer role of EBF1 was not explicitly dissected in this study, its involvement in the NR2F2 regulatory network indirectly supports its tumor-suppressive role in PCa." (PMID 40508012, 2025).
cancer (37 papers, 2013 to 2025). A tumor composed of atypical neoplastic, often pleomorphic cells that invade other tissues. "Additionally, whole-exome sequencing of clinical samples revealed somatic mutations in EBF1 in bilateral BC tissues from a single patient, identifying EBF1 as a potential cancer driver gene in synchronous bilateral BC." (PMID 40508012, 2025). "Beyond the previously discussed cancers, the role of EBF1 in other solid tumors is gradually being uncovered, although its function exhibits considerable heterogeneity." (PMID 40508012, 2025). "We focused on KLF2 (Krüppel-Like Factor 2), ETS2 (ETS Proto-Oncogene 2), and EBF1 (Early B Cell Factor 1), which are usually deregulated in several cancers, including BC, and have several putative binding sites on the EGFL7 gene." (PMID 39796183, 2025). "The Kyoto Encyclopedia of Genes and Genomes (KEGG) analysis demonstrated that EBF1 suppressed “Pathway in Cancer”." (PMID 33854627, 2021). "EBF1 can interact with the methylcytosine dioxygenase enzyme TET2 in several cancer types, suggesting a role of EBF1 in regulating DNA methylation." (PMID 33061809, 2020). "Activated EBF1 can upregulate target gene CD164, which is a cancer-promoting gene associated with tumorigenesis involved in the regulation of cell proliferation and adhesion." (PMID 31126066, 2019). "By comparing the methylomes of IDH-mutant cancers, the authors identify the transcription factor EBF1 as a partner of TET2, suggesting a possible means for targeting TET2 to specific DNA sequences." (PMID 23863747, 2013). "Still, the cancer-related research on EBF1 is predominantly focused on the hematological system." (PMID 40508012, 2025). "Finally, early B-cell factor 1 (EBF1) has been identified as a TET2 interaction partner in IDH-mutant cancers." (PMID 36213002, 2022). "In addition, RNA sequencing analysis suggested that EBF1 is involved in suppression of numerous pathways in cancer." (PMID 33854627, 2021). "To address whether the mutations found in our study could be causally implicated in ESS development, we queried the cancer Gene Census and found four mutations (SRGAP3, EBF1, IRF4 and PPARG)." (PMID 26429873, 2015). "Therefore, we hypothesized that ZNF521 may promote cancer progression via suppression of EBF1 activity in GC." (PMID 36397644, 2023). "Several studies have highlighted the oncogenic potential of EBF1 in CRC, demonstrating its involvement in reshaping the TME and directly regulating the biological behavior of cancer cells." (PMID 40508012, 2025). "The top 200 linear model genes were screened against the known cancer driver genes in Cancer Gene Census, yielding four hits: BUB1B, EBF1, PPARG, and RECQL4." (PMID 41048341, 2025). "Since the transcription of miRNAs with anti-oncogenic activity is often regulated by TFs that are themselves oncosuppressors, we focused on EBF1, ETS2, and KLF2, which are frequently deregulated in cancer, and can bind to the EGFL7/miR-126 promoter regions." (PMID 39796183, 2025). "Our current study identified the ZNF521/EBF1/AKR1B1 axis, which is hyperactivated in GC and plays important role in promoting cancer cell growth, migration, and invasion." (PMID 36397644, 2023). "Overexpression of EBF1 inhibited cancer cell proliferation, but overexpression of AKR1B1 reversed the inhibitory effect of EBF1 on cell growth." (PMID 36397644, 2023). "Interestingly, we found that one gene (EBF1) discovered in the consensus between DEA, elastic net logistic regression, and PCA was also annotated as a canonical cancer gene in NCG." (PMID 40788820, 2025).